ELK1 (ETS transcription factor ELK1)
Diseases named in the same sentence as ELK1 in open-access papers (continued):
Sharing a sentence is not in itself a finding about the gene and the disease.
hepatocellular carcinoma (15 papers, 2014 to 2025). A malignant tumor that arises from hepatocytes. "A 2002 study conducted on hepatoma cells, concluded that prolonged ELK1 phosphorylation can inhibit the growth of the cells." (PMID 40862737, 2025). "Consistent with our findings, the up-regulation of ELK1 has been previously reported in hepatocellular carcinoma tissues while the depletion of ELK1 exerts an inhibitory effect on cell migration and invasion." (PMID 32670874, 2020). "To confirm the role of the P300/Elk1 pathway in promoting aPKC-ι transcription, we studied the specific protein-DNA combination between Elk1 and aPKC-ι promoter in hepatoma cells by Ch-IP assay." (PMID 32144235, 2020). "Double immunofluorescent staining revealed the localization of P300 and Elk1 proteins were both in the nucleus of hepatoma cells." (PMID 32144235, 2020). "Studies involving ELK1 in cervical, endometrial, and liver carcinomas have also been reported in the past decade." (PMID 28206956, 2017). "In this study, the molecular mechanism of protein kinase C alpha (PKCα) gene regulation in hepatocellular carcinoma (HCC) involving Ets-like protein-1 (Elk-1) and myeloid zinc finger-1 (MZF-1) was investigated." (PMID 26010542, 2015). "Another study on cervical, endometrial, and liver carcinoma demonstrated that the oncogene CIP2A, is regulated by ELK1 and ETS1 and ultimately leads to augmented cell proliferation." (PMID 40862737, 2025). "Similarly, in another study, oral administration of WA (4 mg/kg) effectively inhibited HepG2-xenografts and diethylnitrosamine (DEN)-induced-hepatocellular carcinoma (HCC) in C57BL/6 mice by elevating the levels of ERK, RSK, ELK1, and DR5 along with decreased expression of Ki67." (PMID 32116665, 2019). "This study uses the human hepatocellular carcinoma (HCC) model to demonstrate that MZF-1 and Elk-1 directly bind to the PKCα promoter and modulate PKCα performance through the interactive cooperation between the two transcription factors." (PMID 26010542, 2015).
lung carcinoma (15 papers, 2015 to 2025). "In recent years, several studies have been conducted in lung cancer concerning ELK1’s role in tumorigenesis and tumor progression." (PMID 40862737, 2025). "Interactions of lung cancer cells with other cell types have also been shown to affect intracellular signaling, including the expression and activation of ELK1." (PMID 40862737, 2025). "Analysis of TCGA database showed that ELK1 expression levels were positively correlated with BCL6 expression levels in human lung cancers." (PMID 36377663, 2022). "Our findings are in line with a previous study demonstrating that activated KRAS proto-oncogene and insulin-like growth factor 1 signaling induce MDM4 expression at least partially via ELK1 in breast, colon, and lung cancer cells." (PMID 33429878, 2021). "Specific examples, ARAF1 and ELK1, have been previously identified as oncogenes in testicular cancers with X-chromosome amplifications, and GRPR has been associated with an increased risk of lung cancer in females." (PMID 37759468, 2023). "Future studies to elucidate the mechanism by which afatinib inhibits Elk-1 may lead to further progress in the development of molecular-targeted therapy for lung cancer." (PMID 25537503, 2015). "Taken together, Elk-1 is confirmed as a target of resveratrol in lung cancer." (PMID 26124921, 2015). "For instance, in lung cancer, BCL6 is regulated by the MAPK/ELK1 axis and facilitates KRAS‐driven tumorigenesis." (PMID 41438489, 2025). "Both ELK1 and PLEK2 were found to be overexpressed in lung cancer, and prognostic value was also attributed to their expression level." (PMID 40862737, 2025). "Given that the KRAS/MAPK/ELK1 axis directly regulates BCL6 expression, we next investigated whether activated BCL6 promoted KRAS-mutant lung cancer." (PMID 36377663, 2022). "Furthermore, ELK1 is known to be activated by the RAS/RAF/MEK/ERK signaling pathway in breast epithelial cells, and RAS activation is one of the mechanisms for EGFR-TKI resistance in lung cancer." (PMID 38397056, 2024). "Immunohistochemistry of the lung cancer tissue sections showed that the expression of CIP2A was frequently observed in the clinical tumor samples from the NSCLC patients and that the expression of CIP2A in the tumor samples was correlated with the expressions of p-AKT and Elk-1." (PMID 25537503, 2015). "Another study reported again that MZF1/ELK1 expression is correlated with that of PKCα in HCC; however, they did not confirm this in BCa or lung cancer." (PMID 40862737, 2025).
pancreatic cancer (14 papers, 2017 to 2025). "Studies have found that ELK1 plays an important role in the pathogenesis of various diseases, such as nasopharyngeal cancer and pancreatic cancer." (PMID 39858170, 2025). "Overexpression of ELK1 further promoted pancreatic cancer cells proliferation, invasion and survival." (PMID 34966781, 2021). "In this study, we have revealed a new mechanism by which ELK1 promotes the progression of pancreatic cancer through LGMN." (PMID 34966781, 2021). "Collectively, these in vivo experiment confirmed our in vitro data and identified ELK1 promoted pancreatic cancer cell proliferation, invasion and survival through LGMN." (PMID 34966781, 2021). "Taken together, these results indicated that transcription factor ELK1 promoted the expression of LGMN in pancreatic cancer cells." (PMID 34966781, 2021). "In conclusive, our results revealed a new mechanism by which ELK1 promoted the progression of pancreatic cancer via LGMN and conferred poor prognosis." (PMID 34966781, 2021). "In conclusion, our results suggest that ELK1 promotes pancreatic cancer progression via LGMN and correlates with poor prognosis." (PMID 34966781, 2021). "In conclusion, our study revealed that ELK1 promoted the proliferation, invasion and survival of pancreatic cancer cells by LGMN." (PMID 34966781, 2021). "Mechanistically, monensin suppresses numerous cancer-associated pathways, such as E2F/DP1, STAT1/2, NFkB, AP-1, Elk-1/SRF, and represses EGFR expression in pancreatic cancer lines." (PMID 30559409, 2018). "Moreover, knocking down of ELK1 reduced pancreatic cancer cells proliferation, invasion and survival, while LGMN restored the malignancy of pancreatic cancer in vitro and in vivo." (PMID 34966781, 2021). "Knocking down of ELK1 inhibited pancreatic cancer cells proliferation, invasion and survival, while LGMN could restore their malignancy." (PMID 34966781, 2021). "To elucidate the role of ELK1 in PDAC, we examined the proliferation, invasion and survival of pancreatic cancer cells." (PMID 34966781, 2021). "It is noteworthy that transcription factors, such as ETS2, JUN, and ELK1, were upregulated in the KRAS mutated CRC, but not in lung and pancreatic cancers." (PMID 33982211, 2021). "We then analyzed the expression of ELK1 and LGMN in four different pancreatic cancer cell lines." (PMID 34966781, 2021).
gastric cancer (12 papers, 2015 to 2025). A primary or metastatic malignant neoplasm involving the stomach. "In gastric cancer, ELK1 has also been credited with a pivotal role in Hedgehog-EMT signaling crosstalk." (PMID 40862737, 2025). "Based on the microarray dataset of gastric cancer GSE49051 in the GEO database, we successfully isolated CXXC4 as a significantly down‐regulated gene in gastric cancer, while the StarBase database revealed a significant up‐regulation of ELK1 in gastric cancer." (PMID 32715641, 2020). "According to Western blot analysis, compared with adjacent normal tissues, the expression of CXXC4 in gastric cancer declined while the level of p‐ELK1 increased." (PMID 32715641, 2020). "More importantly, CXXC4 has been found to inhibit the extent of ETS domain‐containing protein‐1 (ELK1) phosphorylation, which is relevant as phosphorylation of ELK1 promotes the development of gastric cancer." (PMID 32715641, 2020). "Inhibition of the CXXC4/ELK1/MIR100HG pathway suppressed the immune escape of gastric cancer cells, highlighting a possible therapeutic target for the treatment of gastric cancer." (PMID 32715641, 2020). "Based on reported studies and bioinformatic analyses, we have been suggested the potential role of CXXC4/ELK1/MIR100HG in gastric cancer." (PMID 32715641, 2020). "The role of ELK1 in promoting the migration of mammary gland-derived cells as well as gastric cancer cells has indeed been confirmed." (PMID 26342199, 2015). "ELK1 has been reported multiple times in the context of Gastric cancer (GC)." (PMID 40862737, 2025). "First, we found highly expressed CXXC4 could inhibit the proliferation of gastric cancer cells and enhance the activation of T cells through phosphorylation of ELK1." (PMID 32715641, 2020). "Interestingly, we found CXXC4 and ELK1 were co‐expressed in gastric cancer using the Chipbase website." (PMID 32715641, 2020). "The StarBase database revealed that ELK1 was highly expressed in gastric cancer." (PMID 32715641, 2020). "The co‐expression relationship between CXXC4 and ELK1 in gastric cancer was obtained from Chipbase." (PMID 32715641, 2020). "In a 2019 study on osteosarcoma cell lines, ELK1 was found to upregulate the oncogenic lncRNA MIR100HG, a finding also reported in gastric cancer by another group." (PMID 40862737, 2025). "We showed that the selective activation of P2RY1 via its agonist, MRS2365, can induce ERK1/2 phosphorylation and subsequent ELK1/c-Fos/c-Jun phosphorylation, suggesting the crucial role of ERK1/2 signaling in gastric cancer cells." (PMID 36879646, 2023). "Here, we reported that tumour suppressor protein CXXC4 was able to improve proliferation of CD3+ T cells through ELK1‐mediated regulation of ERK1/2 axis, resulting in an enhanced immune effect to gastric cancer cells." (PMID 32715641, 2020). "ELK1 induced TRPM2-AS and enhances the growth of gastric cancer cells via miR-195/HMGA1 signaling." (PMID 34455918, 2021). "Moreover, ELK1 plays a key role in eliciting EMT in non-small cell lung cancer (NSCLC) and gastric cancer cells." (PMID 31289617, 2019). "The increased expression of APIP in gastric cancer cells enhances the HRG-β1/ERBB3-induced activation of AKT and ERK1/2 which stimulate cell proliferation and positively increase tumorigenesis by elevating ELK-1, C-FOS or cyclin D1." (PMID 26942872, 2016). "However, the relationship between CXXC4 and ELK1 in gastric cancer is not clear." (PMID 32715641, 2020).
glioma (12 papers, 2014 to 2025). A benign or malignant brain and spinal cord tumor that arises from glial cells (astrocytes, oligodendrocytes, ependymal cells). "GATA2 has been directly implicated in promotion of glioma through the EGFR/ERK/Elk-1 pathway, further indicating its potential to forward tumor development in GBM." (PMID 32513296, 2020). "ELK1 was reported to promote glioma cell proliferation by promoting the expression of the lncRNA PSMB8-AS1." (PMID 40862737, 2025). "Regarding glioma, a substance isolated from the fruitbody of Trogia venenata (commonly known as little white mushroom) named Phragmunis A, was found to exhibit cytotoxicity on glioma cells via targeting of the ELK1/SRF complex." (PMID 40862737, 2025). "Several mechanisms of ELK1 activity have been described in gliomas, indicating the TF’s role in multiple aspects of the disease." (PMID 40862737, 2025). "Inhibition of ELK1 activity had also been mentioned in Human bronchial epithelial (HBE) cells; however, this was the first mention of ELK1 inhibition by PI3K-AKT inhibition in gliomas/glioblastomas." (PMID 40862737, 2025). "Further study using RNA sequence and phospho-specific antibody microarray assays identified JNK/ELK1 signaling was up-regulated by RTEL1 in glioma cells through ROS." (PMID 38532312, 2024). "Collectively, our results showed that RTEL1 significantly facilitated phosphorylation of JNK signaling and the downstream transcription factor ELK1 in the tumorigenesis of glioma cells." (PMID 38532312, 2024). "It should be noted, however, that posttranslational modifications such as phosphorylation and SUMOylation regulate ELK1 protein, which can differ among gliomas and must be studied in more detail." (PMID 33672811, 2021). "Pharmaceuticals targeting ELK1 in ovarian cancer and gliomas." (PMID 40862737, 2025). "Another interaction that has been documented in glioma is that of ELK1 with CAV2." (PMID 40862737, 2025). "ELK1 has also been reported in the most aggressive glioma subtype, namely glioblastoma (GBM)." (PMID 40862737, 2025). "In glioma, ELK1 has also been investigated as a promoter of EGR1 transcription." (PMID 40862737, 2025). "We also found that RTEL1 might promote glioma tumorigenesis through JNK/ELK1 cascade and ROS signaling." (PMID 38532312, 2024). "PSMB8-AS1 activated by ELK1 promotes cell proliferation in glioma via regulating miR-574-5p/RAB10." (PMID 35024796, 2022). "Indeed, the p-ERK, p-c-Fos, and p-ELK1 levels were decreased in glioma cells transfected with the miR-3591-3p mimic while transfection of the miR-3591-3p inhibitor led to the opposite trend." (PMID 36085418, 2022). "There is a Elk-1 binding site in Egr-1 promoter, and in C6 glioma cells, ERβ-activated Egr-1 transcription is through ERK/Elk-1 pathway." (PMID 25004251, 2014). "Targeting of ELK1-mediated gene transcription is a concept investigated not only in glioma but in several tumors." (PMID 40862737, 2025). "In conclusion, our results suggested that RTEL1 promotes glioma tumorigenesis through JNK/ELK1 cascade and indicate that RTEL1 may be a prognostic biomarker in gliomas." (PMID 38532312, 2024). "Shen once reported that ELK-1 could activate PSMB8-AS1, which could modulate miR-574-5p/RAB10 and promote cell proliferation in glioma." (PMID 34281486, 2021). "The objective of this study is to investigate the role of alternative splicing in modulating the transcriptional regulation in brain lower grade glioma (LGG), especially transcription factor ELK1, which is closely related to various disorders, including Alzheimer’s disease and Down syndrome." (PMID 29780667, 2018). "The analysis of regulon activity scores showed that, while ELK-1 and ETS2 showed high regulon activity in the non-tumor condition (magenta), ETV1 showed a high activity score on mainly grade 2 glioma (green)." (PMID 33671331, 2021).
ovarian carcinoma (12 papers, 2012 to 2025). A malignant neoplasm originating from the surface ovarian epithelium. "The direct regulation of BRCA1, variations in which are linked to increased risks of breast and ovarian cancers, by ELK1/c-Fos/Jun has also been documented." (PMID 34966781, 2021). "Although an ELK-1(K35N) mutation has been observed in an ovarian carcinoma, this is the first report to identify mono-ubiquitination of K35 as a modulator of ELK-1 activity and USP17 as the enzyme responsible for its removal." (PMID 30854565, 2019). "Cox's regression analysis indicated that FIGO stage and nuclear expression of ELK1 and c-Rel are independent risk factors that correlate strongly with the prognosis of ovarian cancer." (PMID 28206956, 2017). "Collectively, we report for the first time that the overexpression of NF-κB1, c-Rel, and ELK1, causing the transcriptional repression of miR-134 in ovarian cancer cells, contribute towards their paclitaxel-resistance via miR-134 and that TAB1 might be a direct target of miR-134 in this process." (PMID 28206956, 2017). "In recent years, elevated expression and/or activation of ELK1 has been reported in various malignancies, including lung, breast, prostate, colorectal, blood, gastric, liver, cervical, thyroid and ovarian cancer." (PMID 40862737, 2025). "ELK1 levels are markedly high in the context of ovarian cancer cells, promoting cell proliferation and migration, and affecting chemotherapy resistance by regulating genes." (PMID 40666290, 2025). "For example, In human ovarian cancer that is resistant to paclitaxel, the expression of miR-134 is suppressed by ELK1, which increases TAB1 levels." (PMID 40666290, 2025). "In Ovarian cancer (OC), ELK1 was reported for the first time in 2002, as a downstream target of Follicle-stimulating hormone (FSH) signaling." (PMID 40862737, 2025). "According to previous reports, NF-κB1, c-Rel, and ELK1 contribute to repressed miR-134 expression by direct binding to promoter region of miR-134 in paclitaxel-resistant human ovarian cancer." (PMID 32284739, 2020). "The results demonstrate that NF-κB1, c-Rel, and ELK1 are involved as transcription factors in repressing miR-134 expression in paclitaxel-resistant ovarian cancer cells." (PMID 28206956, 2017). "To investigate the effect of NF-κB1, c-Rel, and ELK1 on ovarian cancer paclitaxel resistance, we transfected siRNA-NF-κB1-2, siRNA-c-Rel-1, and siRNA-ELK1-2 (siRNA-NC) independently into SKOV3-TR30 cell." (PMID 28206956, 2017). "Moreover, the ongoing activation of the ERK/ELK1 pathway in ovarian cancer is discussed, particularly regarding its role in cell proliferation, and it is highlighted that inhibiting ERK1/2 can effectively curtail tumor expansion." (PMID 40666290, 2025). "Additionally, the downregulation of ELK1 has been shown to promote apoptosis and repress proliferation by increasing miR-134 expression in paclitaxel-resistant ovarian cancer cells." (PMID 33621196, 2021). "Promoter hypomethylation induced upregulation of other cancer-associated genes in ovarian cancer includes maspin (SERPINB5), MCJ, and SNCG (synucelin-γ), which encodes an activator of the MAPK and Elk-1 signaling cascades." (PMID 31608277, 2019). "In this study, we identified TFs including NF-κB1, c-Rel, and ELK1 as the factors that might inhibit miR-134 expression and independently render paclitaxel resistance in ovarian cancer cells." (PMID 28206956, 2017). "We also observed that the NF-κB1, c-Rel, and ELK1 expression was significantly upregulated both at mRNA and protein levels in paclitaxel-resistant SKOV3-TR30 ovarian cancer cells than the parental SKOV3 cell line." (PMID 28206956, 2017). "In combination, these results demonstrate that NF-κB1, c-Rel, and ELK1 bind to their respective recognition sites in the putative promoter region of miR-134 and repress its expression in paclitaxel-resistant SKOV3-TR30 ovarian cancer cells." (PMID 28206956, 2017).
ovarian carcinoma (continued). "In the present study, we observed for the first time that NF-κB, c-Rel, and ELK1 bind to their respective recognition sites in the putative promoter region of miR-134 and suppress its expression in paclitaxel-resistant SKOV3-TR30 ovarian cancer cells." (PMID 28206956, 2017). "Together, these results provide sufficient evidence to conclude that TFs of NF-κB1, c-Rel, and ELK1 transcriptionally repress miR-134 expression, thereby leading to TAB1 upregulation and contributing to ovarian cancer chemoresistance." (PMID 28206956, 2017). "Monensin suppresses multiple cancer-related pathways including Elk1/SRF, AP1, NFκB and STAT, and reduces EGFR expression in ovarian cancer cells." (PMID 26639992, 2015). "Monensin was shown to target multiple cancer-related signaling pathways such as Elk1/SRF, AP1, NFκB and STAT, and suppresses EGFR expression in ovarian cancer cells." (PMID 26639992, 2015). "ELK1 is a transcription factor belonging to the ETS oncogene family and induces endothelial-to-myofibroblast transition of tumor endothelial cells, which plays an important role in breast and ovarian cancers." (PMID 33671441, 2021). "Monensin was shown to target multiple cancer-related signaling pathways including Elk1/SRF, AP1, NFκB and STAT, and suppress the expression of EGFR, but not IGF-1R, in ovarian cancer cells." (PMID 26639992, 2015).